RPL13 (ribosomal protein L13)
Description:
Component of the ribosome, a large ribonucleoprotein complex responsible for the synthesis of proteins in the cell. The small ribosomal subunit (SSU) binds messenger RNAs (mRNAs) and translates the encoded message by selecting cognate aminoacyl-transfer RNA (tRNA) molecules (Probable). The large subunit (LSU) contains the ribosomal catalytic site termed the peptidyl transferase center (PTC), which catalyzes the formation of peptide bonds, thereby polymerizing the amino acids delivered by tRNAs into a polypeptide chain (Probable). The nascent polypeptides leave the ribosome through a tunnel in the LSU and interact with protein factors that function in enzymatic processing, targeting, and the membrane insertion of nascent chains at the exit of the ribosomal tunnel (Probable). As part of the LSU, it is probably required for its formation and the maturation of rRNAs. Plays a role in bone development.
Synonyms: BBC1; D16S444E; L13; eL13; D16S44E; SEMDIST
Tractability: Small molecule: an approved drug acts on it; a structure with a bound ligand is known; a high-quality ligand is known. PROTAC: UniProt records ubiquitination sites on it; ubiquitination databases record sites on it; its protein half-life has been measured; a small molecule that binds it is known. Other modalities: a drug acting on it is in phase 2 or 3 trials.
Target class: Other cytosolic protein
Gene: Protein-coding gene on chromosome 16 (89,560,637 to 89,567,834, forward strand). Ensembl gene ENSG00000167526.
Subcellular location: Cytoplasm
Subcellular location (Human Protein Atlas): Cytosol; Endoplasmic reticulum; Nucleoli
Pathways (Reactome):
Metabolism of proteins: Eukaryotic Translation Termination; Formation of a pool of free 40S subunits; GTP hydrolysis and joining of the 60S ribosomal subunit; L13a-mediated translational silencing of Ceruloplasmin expression; PELO:HBS1L and ABCE1 dissociate a ribosome on a non-stop mRNA; Peptide chain elongation; Ribosome Quality Control (RQC) complex extracts and degrades nascent peptide; SRP-dependent cotranslational protein targeting to membrane; ZNF598 and the Ribosome-associated Quality Trigger (RQT) complex dissociate a ribosome stalled on a no-go mRNA
Metabolism of RNA: Major pathway of rRNA processing in the nucleolus and cytosol; Nonsense Mediated Decay (NMD) enhanced by the Exon Junction Complex (EJC); Nonsense Mediated Decay (NMD) independent of the Exon Junction Complex (EJC)
Cellular responses to stimuli: Response of EIF2AK4 (GCN2) to amino acid deficiency
Developmental Biology: Regulation of expression of SLITs and ROBOs
Disease: Viral mRNA Translation
Metabolism: Selenocysteine synthesis
Gene Ontology:
Molecular function: protein binding; RNA binding; structural constituent of ribosome
Biological process: bone development; cytoplasmic translation; negative regulation of myoblast fusion; spermatogenesis; striated muscle contraction; translation
Cellular component: cytoplasm; cytosol; cytosolic large ribosomal subunit; cytosolic ribosome; endoplasmic reticulum; membrane; nucleolus; nucleus; ribosome; synapse
Genetic constraint (gnomAD): Loss-of-function variants: 1 observed, 18.97 expected, observed/expected ratio (o/e) 0.0527, 90% interval 0.018 to 0.25. The synonymous counts are far from expectation, so gnomAD's model fits this gene poorly and the ratio says little. Missense variants: 289 observed, 261.55 expected, observed/expected ratio (o/e) 1.11, 90% interval 1 to 1.22. Synonymous variants: 143 observed, 108.55 expected, observed/expected ratio (o/e) 1.32, 90% interval 1.15 to 1.51.
Homologues: Orthologues: chimpanzee RPL13 (99% identical), dog RPL13 (99% identical), guinea pig RPL13 (99% identical), macaque RPL13 (99% identical), mouse Rpl13 (98% identical), rat Rpl13 (97% identical), rat LOC100361259 (96% identical), rat LOC100360491 (92% identical), tropical clawed frog rpl13 (89% identical), zebrafish rpl13 (87% identical), Drosophila melanogaster RpL13 (63% identical), Caenorhabditis elegans rpl-13 (56% identical).
Diseases named in the same sentence as RPL13 in open-access papers:
RPL13 is named in the same sentence as 43 diseases in open-access papers, as found by Europe PMC text mining. Sharing a sentence is not in itself a finding about the gene and the disease. The quoted sentences say what the papers report.
spondyloepimetaphyseal dysplasia (6 papers, 2021 to 2025). An osteochondrodysplasia that results in abnormalities of bone growth in the vertebral column, epiphysis, and metaphysis. "Spondyloepimetaphyseal dysplasia type Isidor-Toutain (RPL13-SEMD) is an autosomal dominant skeletal dysplasia caused by heterozygous pathogenic variants in the RPL13 gene, encoding the ribosomal protein eL13." (PMID 40725227, 2025). "The CRISPR/Cas9 editing of zebrafish rpl13 gene has been proposed for spondyloepimetaphyseal dysplasia (SEMD-RPL13 type), as recently found in several human families." (PMID 34490030, 2021).
breast cancer (5 papers, 1997 to 2023). A primary or metastatic malignant neoplasm involving the breast. "RPL13 encodes a component of the 60S ribosomal subunit that is expressed at significantly higher levels in benign breast lesions than in breast carcinomas." (PMID 36775056, 2023). "To further verify the identified target genes that showed significant changes in DE and DM patterns in response to the combination treatment, we evaluated the expression of Pdx1, Tmem132d, Get4, Rpl13 and Ndufa1 genes in mouse mammary tumors using qRT-PCR." (PMID 33947955, 2021). "Our analysis confirmed the down-regulation of RPL13, and newly identified down-regulation of HDAC1, ANP32A, and the up-regulation of SNX2 as having the worst prognostic effects in normal-subtype breast cancer tumors (panels C4–C7)." (PMID 35971177, 2022). "Together, combining our systems biology analysis with a dual validation approach, we have confirmed/validated only two intrinsic biomarkers, RPL13 and RPL38, for Luminal-A breast cancers." (PMID 35971177, 2022). "Surprisingly, in our omics data, we also observed down-regulation for RPL13 expression (PRG treatment only) and RPL38 expression (PRG treatment and CSC-KD) in nPR(+) T47D cells (panel A1), validating their role as intrinsic biomarkers in Luminal-A breast cancers." (PMID 35971177, 2022).
viral infection (4 papers, 2020 to 2025). "Therefore, RPL13 mediates the activation of the innate immune pathway in PK-15 cells when stimulated by either an immune inducer or viral infection." (PMID 34093518, 2021). "In addition, another variant of RPL13 was induced in the presence of PVA, which also suggests a role for RPL13 in virus infection." (PMID 32727361, 2020). "Different RPs like RPL10, RPL13, RPL18, RPL24, and RPS6 are involved in viral infections of plants." (PMID 33995313, 2021).
Alzheimer disease (3 papers, 2012 to 2022). A progressive, neurodegenerative disease characterized by loss of function and death of nerve cells in several areas of the brain leading to loss of cognitive function such as memory and language. "One study has reported that the DNA methylation changes of RPL13 were associated with the onset of Alzheimer’s disease (AD)." (PMID 35153787, 2022). "Due to high stability, GUSB was noted as a suitable RG in lung and ovarian cancers, whereas RPL13 was the best RG in Alzheimer’s disease and in mesenchymal stem cell study." (PMID 25225161, 2014). "Therefore, we assume that there is an unknown link between the pseudogene and Alzheimer’s disease, possible mediated by the original RPL13 gene." (PMID 23066814, 2012).
gastric cancer (2 papers, 2021 to 2023). A primary or metastatic malignant neoplasm involving the stomach. "For example, overexpression of RPL13 has been demonstrated to promote chemoresistance in gastric cancer." (PMID 37373047, 2023). "Many RPs are found affected in gastric cancer (GC) including RPS13, RPL23, RPS27, RPL6, RPL13 and RPL15." (PMID 34873618, 2021).
kidney cancer (2 papers, 2018 to 2020). Primary or metastatic malignant neoplasm involving the kidney. "Among the nine RBPs, EEF1A2, and RPL13 have been reported to be associated with tumorigenesis and progression of kidney cancer patients." (PMID 33133154, 2020). "Furthermore, clinical correlations of the prostate, uterine and kidney cancer t-SNE clusters described here with relative overexpression of RPL13 were inconsistent." (PMID 29530001, 2018).
melanoma (2 papers, 2024 to 2025). A malignant, usually aggressive tumor composed of atypical, neoplastic melanocytes. "In agreement with the differential abundance analysis, APCA+ on the cell type indicates that monocytes are characterized by high intensities of CORO1A, LCP1, TMSB4X, and RPL13, while melanoma cells are characterized by higher intensities of VIM and MCALL1." (PMID 40775377, 2025). "In conclusion, this study provides insight into the potential mechanisms underlying Si162 resistance in melanoma cells and identified 5 genes (CNTN6, ADD1, FGF18, C18orf25, and RPL13) as potential prognostic biomarkers for Si162 resistance." (PMID 38665777, 2024).
spondyloepimetaphyseal dysplasia, Isidor-Toutain type (2 papers, 2020 to 2025). "Spondyloepimetaphyseal dysplasia type Isidor-Toutain (OMIM#618728) is a rare autosomal dominant skeletal dysplasia caused by heterozygous variants in the RPL13 gene." (PMID 40725227, 2025).
and mouth disease (1 paper, 2025). "RPL13 promotes IRES-driven translation of foot and mouth disease in a DDX3-dependent helicase." (PMID 40007003, 2025).
atherosclerosis (1 paper, 2023). A disease characterized by the build-up of fatty material and calcium deposition in the arterial wall resulting in partial or complete occlusion of the arterial lumen. "In summary, RPL13 inhibits macrophage-induced inflammation and atherosclerosis by inhibiting the translation of inflammatory genes such as CCL22, CXCL13a, and CCR3." (PMID 36617563, 2023). "The protective effect of RPL13 on atherosclerosis may be related to its translational silencing activity: the deletion of RPL13 promotes the translation of mRNAs for CCL22, CXCL13, and CCR3 in macrophages, causing increased expression of inflammatory cytokines." (PMID 36617563, 2023).
congenital heart disease (1 paper, 2020). A heart disease that is present at birth. "Furthermore, RPL13/eL13 was discovered to be a candidate disease gene in patients with congenital heart disease, with heart-specific RPL13/eL13 knockdowns compromising embryonal heart development in fruit fly." (PMID 33575632, 2020).
congenital myopathies (1 paper, 2025). "In the context of RYR1‐related congenital myopathies the finding that RPL13 is significantly down‐regulated in dHT muscle spindles may be of relevance." (PMID 41091627, 2025).
COVID-19 (1 paper, 2025). A disease caused by infection with severe acute respiratory syndrome coronavirus 2. "In COVID-19, these included RPL13A, RPL6, RPL13, RPLP2, RPS11, UBA52, and the ribosomal pseudogene RPL13AP20." (PMID 41020849, 2025).
influenza (1 paper, 2025). An acute viral infection of the respiratory tract, occurring in isolated cases, in epidemics, or in pandemics; it is caused by serologically different strains of viruses (influenzaviruses) designated A, B, and C, has a 3-day incubation period, and usually lasts for 3 to 10 days. "For influenza, discriminatory ribosomal genes included RPL7A, RPL13, RPL18, RPL23A, RPLP2, RPS2, and RPS4X." (PMID 41020849, 2025).
kidney clear cell carcinomas (1 paper, 2018). "In contrast, kidney clear cell carcinomas with high RPL13 expression tended to be of higher pathologic grade and were associated with significantly poorer survival." (PMID 29530001, 2018). "Finally, tumor clusters overexpressing RPL13 were found in prostate, uterine and kidney clear cell carcinoma and shared similar patterns of expression of 42 other RPTs." (PMID 29530001, 2018).
promyelocytic leukemia (1 paper, 2019). "Thus, the top two AML genes, MPO (myeloperoxidase) and PML (promyelocytic leukemia) have the GCHs 22.96 and 21.95, below those of the 56th and the 59th ranked ribosomal proteins RPL29 (23.64) and RPL13 (22.12)." (PMID 31349573, 2019).
schizophrenia (1 paper, 2015). A major psychotic disorder characterized by abnormalities in the perception or expression of reality. "This analysis demonstrated that the levels of eIF2α, RPL13, RPL13A, RPL18A, RPL27A and RPL32 were reduced in schizophrenia patient-derived cells in comparison with controls." (PMID 26485547, 2015).
tumor (14 papers, 1997 to 2025). "In kidney renal clear cell carcinoma (KRCCC), researchers found that RPL13 was associated with the prognosis of tumor patients." (PMID 34993140, 2021). "Among them, Rpl13, Rpl14, and Rpl18A all exist in the 60s ribosomal subunit, and previous studies have shown that they are tumor suppressor genes." (PMID 38544816, 2024). "The qRT-PCR analysis on cell lines confirmed the SAGE results and validated the over-expression of PDFGR and RPL13 in the East tumor libraries." (PMID 18302799, 2008). "Different pattern occurs for RG pair selection, since only RPL13 + RPLP0 selected by the GeNorm algorithm fulfils statistical criteria; therefore, for matched tumor-control-metastasized ccRCC samples (group IV) RPL13 + RPLP0 pair may be considered for normalization in gene expression studies." (PMID 25225161, 2014). "RPL13 gene was the most stable RG in analysis of 35 primary tumor nonmetastatic versus 35 mccRCC samples and matched metastasized T/C/M samples (n = 12, each group)." (PMID 25225161, 2014). "Unlike RPL3 and RPS4X, RPL13’s role in tumor development is less clear." (PMID 29530001, 2018). "RPL13 activation has been described in a subset of gastrointestinal malignancies and correlated with greater proliferative capacity and attenuated chemoresistance, but further evidence for a role of RPL13 in tumor development is lacking." (PMID 29530001, 2018). "GUSB was the most stable RG in group I (all samples), GAPDH in group II (paired 70 T + 70 C), followed by RPL13 in groups III (35 nonmetastatic vs 35 mccRCC) and IV (matched tumor-metastasized control group of samples)." (PMID 25225161, 2014).
cancer (8 papers, 2014 to 2024). A tumor composed of atypical neoplastic, often pleomorphic cells that invade other tissues. "Additionally, higher expression levels of RPL13, a ribosomal protein, were observed in the Si162-resistant group, indicating its potential involvement in cancer cell growth through protein synthesis regulation." (PMID 38665777, 2024). "The robust downregulation of RPL13 in all six cancer nodules (by −1.70×/−1.38×/−1.36× in “P”/”Q”/“M” vs. “Z” and by −2.15×/−1.30×/−1.50× in “A”/”B”/”C” vs. “N”) explains the reduced immune response in cancer." (PMID 35723406, 2022). "Other recurrent RPT expression patterns across cancer cohorts involved RPS4X, RPL13, RPL8 and RPL30." (PMID 29530001, 2018). "Interestingly, we observed that GAPDH, GUSB, IPO8, RPL13, RPL32, and UBC genes, as well as RPLP0 + TBP, RPL13 + RPL32, RPL13 + RPLP0, and ACTB + TBP RG pairs, were the only assays whose expression did not depend (P > 0.05) on cancer progression." (PMID 25225161, 2014).
infection (6 papers, 2010 to 2025). The state of being infected such as from the introduction of a foreign agent such as serum, vaccine, antigenic substance or organism. "FMDV infection inhibited the gene and protein expression of RPL13 in PK-15 cells, and this inhibition increased continuously as the infection lasted." (PMID 34093518, 2021). "Differential induction of ribosomal protein family members (e.g., RPL13) during infection of A. thaliana with turnip mosaic virus (genus Potyvirus) has also been documented." (PMID 32727361, 2020). "We also found that the overexpression of RPL13 promoted the expression of NF-κB–Luc and IFN-β–Luc induced by FMDV infection, whereas the knockdown of RPL13 inhibited the FMDV-infection-induced expression of NF-κB–Luc and IFN-β–Luc." (PMID 34093518, 2021). "Overall, it was found that RPL13 gene was the most stable expressed gene in the examined tissues of SPF layer chickens regardless of an infection with H. meleagridis." (PMID 27765062, 2016).
skeletal dysplasia (5 papers, 2020 to 2025). Any Mendelian diseases that affects growth and development of the skeleton. "Current evidence suggests that RPL13-SEMD appears to be the only known isolated skeletal dysplasia primarily affecting large joints and caused by ribosomal dysfunction." (PMID 40725227, 2025). "Mutations in RPL13 were found to cause severe skeletal dysplasia, and its expression was found to be localized to the hypertrophic zone in murine growth plate chondrocytes." (PMID 38732249, 2024). "RPL13/eL13, at ∼80% identity between human and zebrafish presents a missense and three splice variants, the latter leading to an 18 aa insertion, with RPL13/eL13 being the cause of a rare ribosomopathy, characterized by skeletal dysplasia." (PMID 33575632, 2020).
neurodegenerative disease (2 papers, 2022). A disorder of the central nervous system characterized by gradual and progressive loss of neural tissue and neurologic function. "RPL13 was previously recommended as a reference gene for neuronal tissue in neurodegenerative disease." (PMID 35031523, 2022). "For this study, we chose two reference genes, PPIA and RPL13, which are relatively stable in the cerebral cortex across many neurodegenerative diseases." (PMID 36129947, 2022).
RPL13 also shares sentences with these, for which no sentence is quoted: prostate carcinoma (2 papers); Atrioventricular canal defect (1); Au-Kline syndrome (1); breast tumour (1); childhood asthma (1); chronic myeloid leukemia (1); congenital hypothyroidism (1); Diabetes (1); foot and mouth disease (1); glioma (1); lung carcinoma (1); lymphoma (1); malignant brain tumors (1); metastatic cancer (1); periodontitis (1); postnatal growth deficiency (1); psoriasis (1); renal cell carcinoma (1); Renpenning syndrome (1); Sepsis (1); uterine cancer (1).